FCN2 (ficolin 2)
Diseases named in the same sentence as FCN2 in open-access papers (continued):
Sharing a sentence is not in itself a finding about the gene and the disease.
lymphoma (2 papers, 2019 to 2020). A malignant (clonal) proliferation of B- lymphocytes or T- lymphocytes which involves the lymph nodes, bone marrow and/or extranodal sites. "Our data suggest moreover a possible association of some FCN2 polymorphisms with multiple myeloma (−857 C>A) or lymphomas (−557 A>G; +6424 G>T)." (PMID 32047495, 2019). "The ROC analysis showed high potential of both ficolin-2 and ficolin-3 to differentiate between AML patients and controls as well as patients suffering from multiple myeloma or lymphomas." (PMID 32601370, 2020). "Both papers documented possible associations of factors specific for the lectin pathway of complement (especially on genetic background) with multiple myeloma or lymphoma (MBL, ficolin-1, ficolin-2) or hospital infections (MASP-2, ficolin-3)." (PMID 32047495, 2019). "The median of ficolin-1 (as well as of ficolin-2 and−3) for patients diagnosed with lymphomas was not compared with the C or MM groups as their previous medication may affect their serum level." (PMID 32047495, 2019).
ovarian tumors (2 papers, 2013 to 2020). "Being a regulator of the lectin complement pathway, FCN2 contributes to innate immune response and is expressed at low levels in ovarian tumors compared to normal ovaries." (PMID 32731407, 2020). "We report for the first time the expression of the FCN2 and FCN3 genes in the ovary, their polymorphisms, and their serum concentrations in patients with ovarian tumours (both malignant and benign) as well as women operated on for reasons unconnected with ovarian tumours." (PMID 23744477, 2013).
pulmonary TB (2 papers, 2013 to 2015). "Distribution of the FCN2 SNP allele frequencies and genotype frequencies in the pulmonary TB group (n = 282) and the control group (n = 254)." (PMID 26379154, 2015). "The present study aimed to investigate the association between SNPs of the FCN2 gene and susceptibility to pulmonary TB in the Chinese Han population." (PMID 26379154, 2015). "As -557 A>G, -64 A>C, and +6424 G>T were linked in pulmonary TB patients, therefore, we assumed that this may affect the ficolin-2 expression and the binding activity of pathogens by influencing the binding ability of N-acetylglucosamine, ultimately affecting the activation of complements." (PMID 26379154, 2015). "The present study is the first to describe the correlation between seven SNPs (-986 G>A, -602 G>A, -557 A>G, -64 A>C, -4 A>G, +6359 C>T, and +6424 G>T) in the FCN2 gene and pulmonary TB." (PMID 26379154, 2015). "Correlation between FCN2 SNPs and pulmonary TB revealed an important role of FCN2 in the pathogenesis of TB." (PMID 26379154, 2015). "A total of seven SNPs in exon 8 (+6359 C>T and +6424 G>T) and in the promoter region (-986 G>A, -602 G>A, -557 A>G, -64 A>C and -4 A>G) of the FCN2 gene were genotyped using the PCR amplification and DNA sequencing methods in the healthy controls group (n = 254) and the pulmonary TB group (n = 282)." (PMID 26379154, 2015). "Therefore, -557 A>G, -64 A>C and +6424 G>T SNPs of the FCN2 gene were correlated with pulmonary TB, and may be protective factors for TB." (PMID 26379154, 2015). "However, all haplotypes with the FCN2 gene polymorphisms were not significantly correlated with pulmonary TB (P > 0.05)." (PMID 26379154, 2015).
scleroderma (2 papers, 2014 to 2016). Scleroderma is a rare autoimmune connective tissue disorder characterized by abnormal hardening of the skin and, sometimes, other organs. "FCN2 and MBL activate the lectin complement pathway and studies have linked this pathway to fibrotic organ manifestations in Scleroderma, including ILD." (PMID 27490795, 2016).
sinusoidal obstruction syndrome (2 papers, 2019 to 2020). "Ficolin-2 has been also considered as a biomarker for post-allo-HSCT sinusoidal obstruction syndrome (SOS)." (PMID 32047495, 2019).
systemic sclerosis (2 papers, 2014 to 2020). A chronic disorder, possibly autoimmune, marked by excessive production of collagen which results in hardening and thickening of body tissues. "On the other hand, two studies found an association between high ficolin-2 and MBL plasma levels and systemic sclerosis associated ILD (SSc-ILD), which was supported by a higher frequency of wild-type FCN2 and MBL2 genotypes in SSc-ILD patients." (PMID 33101280, 2020). "MBL levels but not ficolin-2 levels correlated with the EUSTAR Systemic Sclerosis Activity Score in diffuse SSc patients (r = 0.49, P = 0.02)." (PMID 25403109, 2014).
Telangiectasia (2 papers, 2014 to 2019). Telangiectasias refer to small dilated blood vessels located near the surface of the skin or mucous membranes, measuring between 0.5 and 1 millimeter in diameter. "MBL levels were significantly elevated in SSc patients with examination findings of pitting, calcinosis and digital ulcers (but not with telangiectasia, pulp atrophy and nailfold capillary dilatation), which was not the case for ficolin-2 levels." (PMID 25403109, 2014).
acute myeloid leukemia (1 paper, 2022). Acute myeloid leukemia (AML) is a group of neoplasms arising from precursor cells committed to the myeloid cell-line differentiation. "FCN2 was positively correlated with most major histocompatibility complexes (MHCs) in LIHC, mesothelioma (MESO), and acute myeloid leukemia (LAML) and negatively correlated with most MHCs in TGCT." (PMID 36425563, 2022).
Autoimmunity (1 paper, 2019). The occurrence of an immune reaction against the organism's own cells or tissues. "Indeed, FCN-2 was also shown to participate in the clearance of dying cells maintaining tissue homeostatis and hence may influence the induction of autoimmunity through mechanisms of the innate immune system." (PMID 30885245, 2019).
bacteremia (1 paper, 2020). "The highest frequency (35.6%) of such high ficolin-2 concentrations was found among patients who experienced infections with no bacteremia/fungaemia [p < 0.000001, OR = 9.99, 95% CI (4.62–21.62) vs. C group]." (PMID 32601370, 2020).
Brain atrophy (1 paper, 2021). Partial or complete wasting (loss) of brain tissue that was once present. "Furthermore, FCN2 and FGG were related to brain atrophy and rate of cognitive decline." (PMID 34366831, 2021).
chronic heart failure (1 paper, 2013). "We hypothesized that the main initiator molecules of the lectin complement pathway mannose-binding lectin (MBL), ficolin-2 and ficolin-3 were related to disease severity and outcome in chronic heart failure." (PMID 23596511, 2013).
chronic tonsillitis (1 paper, 2023). "In this study, we investigated the associations between the SNPs of FCN2 (rs17514136, rs3124953, and rs3124954) and susceptibility to chronic tonsillitis among adult patients in the Polish population." (PMID 36833169, 2023). "In the present study, we investigated the associations between the selected single nucleotide polymorphisms (SNPs) of the FCN2 gene and chronic tonsillitis in the Polish population." (PMID 36833169, 2023). "Furthermore, future investigations are needed to clarify the possible associations between the selected FCN2 SNPs and clinical manifestations of patients, and L-ficolin serum concentration in patients with chronic tonsillitis." (PMID 36833169, 2023). "Moreover, the FCN2 CT genotype of rs3124954 was associated with a higher risk of chronic tonsillitis, while the CC genotype of rs3124954 decreased this risk." (PMID 36833169, 2023). "Our findings demonstrate that FCN2 rs3124954 may be associated with chronic tonsillitis in the Polish adult population." (PMID 36833169, 2023). "Our results indicate that the FCN2 CT genotype of rs3124954 was associated with a higher risk of chronic tonsillitis, while the CC genotype of rs3124954 could decrease the risk of inflammation." (PMID 36833169, 2023). "Our findings demonstrate that FCN2 rs3124954 may contribute to susceptibility to chronic tonsillitis in the Polish population." (PMID 36833169, 2023).
coronary heart disease (1 paper, 2017). "Nevertheless, the associations of PTX3, ficolin-2 and MASP-3 may uncover potential new causal mechanisms in the development and progression of coronary heart disease and risk for MI, lead to the generation of new hypotheses and suggest improvements to existing explanatory models." (PMID 28216633, 2017).
deficiency (1 paper, 2021). "The impact of IgG or IgA subclass deficiency in the setting of MBL deficiency or low ficolin-2 concentrations is unknown." (PMID 34391418, 2021).
fibrosis (1 paper, 2022). the formation of excess fibrous connective tissue in an organ or tissue in a reparative or reactive process. "We also described the in silico strategy used to identify FCN-2 and other protein candidates that are potentially functional in fibrosis diagnosis." (PMID 35269955, 2022). "In the present study, we assessed the plasma FCN-2 levels in a well-histologically characterized NAFLD obese cohort and evaluated its potential use for fibrosis diagnosis." (PMID 35269955, 2022).
Left ventricular dilatation (1 paper, 2018). Enlargement of the chamber of the left heart ventricle. "Higher baseline ficolin-2 levels were associated with left ventricular dilatation after STEMI." (PMID 29910807, 2018).
leishmaniasis (1 paper, 2012). Infectious disease that is transmitted through the bite of hematophagous female phlebotomine sand flies. "In this study, we aim to investigate the contribution of ficolin-2 (FCN2) gene polymorphisms to the susceptibility for leishmaniasis caused by L. tropica in a Syrian cohort." (PMID 22457818, 2012). "In the current study, we aim to investigate the role of five functional FCN2 gene polymorphisms (−986G/A, −602G/A, −4A/G, +6359C/T and +6424G/T) for a possible association to the leishmaniasis outcome in a Syrian cohort." (PMID 22457818, 2012). "Overall, we present evidence that FCN2 polymorphisms may be an additional factor contributing to the susceptibility to leishmaniasis." (PMID 22457818, 2012). "FCN2 haplotypes in Cutaneous Leishmaniasis patients and healthy controls." (PMID 22457818, 2012). "Although the role of ficolin-2 in the interaction with the Leishmania surface remains to be established, these results indicate a role for this molecule in leishmaniasis and represent another example how seemingly disadvantageous polymorphism can be beneficial in a population." (PMID 22457818, 2012).
lepromatous leprosy (1 paper, 2020). A chronic communicable infection which is a principal or polar form of leprosy. "Nevertheless, some associations were lost after multivariate logistic correction (FCN1*3C2, FCN2*AGAAGC, and FCN2*GGGCAC with lepromatous leprosy/HBV infection and MBL2*HYPA, MBL2*LYQC, FCN2*GGGCAC with non-lepromatous leprosy/HBV infection) or due to low sample size (MASP1*AC_CTG, FCN3*2B2.2A)." (PMID 33643280, 2020).
liver cirrhosis (1 paper, 2011). "However, the reason why ficolin-2 serum level in patients with liver cirrhosis is lower is yet to be elucidated." (PMID 22140517, 2011).
liver diseases (1 paper, 2011). "Overall, our data suggests that Ficolin-2 not only play an important role in the pathogenesis of HBV infection but also a functional role in other liver diseases caused by HBV." (PMID 22140517, 2011).
metastatic tumour (1 paper, 2016). "Six genes were associated with tumour pathologic PT and tumour stage; among these, high expression of INTS8 and UBAP2L, and low expression of ACSM3, FCN2, LCAT, and MT1G, was significantly associated with metastatic tumour and late stage (P ≤ 0.05)." (PMID 27567667, 2016).
Myalgia (1 paper, 2025). "The change in FCN2 levels from 0 h to 15 min postexercise positively correlated with baseline myalgia." (PMID 40465195, 2025). "We also observed a positive correlation between the change in EV ficolin‐2 (FCN2) levels from 0 h to 15 min postexercise and the severity of myalgia at 0 h." (PMID 40465195, 2025).
oral squamous cell carcinoma (1 paper, 2022). "Some studies found that FCN2 as a potential biomarker may have diagnostic value for oral squamous cell carcinoma." (PMID 35928441, 2022).
parasitemia (1 paper, 2025). "When we examined for possible association between ficolin-2 and parasitemia, none was found." (PMID 40422078, 2025).
pneumococcal infection (1 paper, 2016). Infections with bacteria of the species streptococcus pneumoniae. "Identifying the mechanism by which ficolin-2 may protect children but not older adults from serotype 11A pneumococcal infection may shed important light on these critical biological processes." (PMID 27896034, 2016).
poisoning (1 paper, 2012). A condition or physical state produced by the ingestion, injection, inhalation of or exposure to a deleterious agent. "Supporting these data, ficolin-2 has recently been shown to bind the E. coli O104:H4 that were responsible for the recent outbreak of food poisoning in Germany causing haemolytic-uremic syndrome (HUS)." (PMID 22666482, 2012).
respiratory distress syndrome (1 paper, 2023). "Multivariate logistic regression analysis indicated that low ficolin-2 increased the possibility of respiratory distress syndrome (RDS) diagnosis [OR=2.05, 95% CI (1.24-3.37), p=0.005]." (PMID 36733481, 2023).
sarcoidosis (1 paper, 2020). Sarcoidosis is a multisystemic disorder of unknown cause characterized by the formation of immune granulomas in involved organs. "Our data suggests an involvement of pattern recognition receptors of the lectin complement pathway in sarcoidosis at the local level with significantly elevated lectin (MBL, ficolin-2, and ficolin-3) as well as complement split products (C4d and C5a) concentrations in the lungs of these patients." (PMID 33101280, 2020).
staphylococcus aureus infection (1 paper, 2022). An infectious process in which the bacteria Staphylococcus aureus is present. "FCN2 may act through Staphylococcus aureus infection, lectins, and other pathways." (PMID 36425563, 2022).
streptococcal infection (1 paper, 2015). Any of the several infectious disorders caused by members of streptococcus, a genus of gram positive bacteria belonging to the family Streptococcaceae. "In addition, SNPs in the FCN2 gene associated with low levels of ficolin-2 level might predispose an individual to recurrent and/or more severe streptococcal infection." (PMID 26379154, 2015).
subarachnoid hemorrhage (1 paper, 2016). A serious neurological disorder characterized by intracranial hemorrhage into the subarachnoid space. "Interestingly, an early decrease in ficolin-2 was also observed in subarachnoid hemorrhage patients." (PMID 26792363, 2016).
type 2 diabetes (1 paper, 2017). "Based on previous IR research, this relationship was as expected because a reduction in ficolin-3, a protein structurally and functionally similar to FCN2, has previously been identified as a biomarker of type 2 diabetes." (PMID 28441961, 2017).
visceral leishmaniasis (1 paper, 2015). A severe form of leishmaniasis characterized by irregular bouts of fever, substantial weight loss, swelling of the spleen and liver, and anemia (which may be serious). "Distribution of FCN2 genotypes and alleles among visceral leishmaniasis cases and healthy controls." (PMID 25965808, 2015). "Association of functional FCN2 haplotypes and visceral leishmaniasis." (PMID 25965808, 2015).
infection (18 papers, 2009 to 2023). The state of being infected such as from the introduction of a foreign agent such as serum, vaccine, antigenic substance or organism. "Specific FCN2 SNPs that are associated with low levels of L-ficolin tend to cause higher susceptibility to infection." (PMID 25642836, 2015). "Our data provide a new immunotherapeutic strategy against TB based on the innate immune molecule ficolin-2 and indicate that ficolin-2 insufficiency is associated with higher susceptibility to infection in humans." (PMID 24040095, 2013). "Our present findings showed that TB patients exhibited significantly lower serum ficolin-2 concentrations, which also suggested that a ficolin-2-deficient host might be more susceptible to infection by these intracellular pathogens." (PMID 24040095, 2013). "In the present work, FCN2 was found to be upregulated in CAD subjects, demonstrating more susceptible to infection in the pathophysiology of CAD." (PMID 32508734, 2020). "The ficolin-2-encoding gene FCN2, was upregulated by 1.52-fold (P = 0.04) with multi-species infection and was downregulated after inoculation with MRSA or PA alone." (PMID 28459043, 2017). "Individuals with polymorphisms in loci containing IL6, IL10, FCN2, RNASE3 and multiple Th17 pathway genes such as IL12B and IL17B had varying worm burden, indicating that these loci may play a role in determining infection intensity." (PMID 38033168, 2023). "Our results inferred that ficolin-2 serum levels were modulated significantly by the infection in VL cases rather than by FCN2 variants." (PMID 25965808, 2015). "We therefore analyzed whether the binding of ficolin-2 to the surface glycolipid portion of Mtb H37Rv could competitively block the adhesion/invasion and infection of Mtb H37Rv in human lung-derived A549 type II alveolar epithelial cells." (PMID 24040095, 2013). "Furthermore, we found that the inhibitory effects of ficolin-2 and ficolin A on Mtb H37Rv infection of A549 cells could be reversed by the addition of ManLAM." (PMID 24040095, 2013). "Next, we confirmed that ficolin-2/ficolin A can significantly block Mtb H37Rv infection of a human lung alveolar epithelial cell line (A549) in vitro, which might contribute to host resistance against virulent Mtb H37Rv infection." (PMID 24040095, 2013). "Furthermore, no impact of the FCN2 promoter (-64 A>C and -4 A>G) or exon 8 (+6359 C>T and +6424 G>T] SNPs on risk of perinatal sepsis or the promoter (-986/-602/-64/-4) SNP on early-onset infection in preterms was found." (PMID 38193083, 2023). "Later, we reported markedly lower ficolin-2 levels in neonates suffering from perinatal sepsis versus those without infections before hospital discharge." (PMID 36499663, 2022).